BMI1 (BMI1 proto-oncogene, polycomb ring finger)
Diseases named in the same sentence as BMI1 in open-access papers (continued):
Sharing a sentence is not in itself a finding about the gene and the disease.
breast carcinoma (continued). "BMI1 expression confers resistance to tamoxifen in ER+ breast cancer, and promotes self-renewal of radio- and temozolomide-resistant breast cancer cells." (PMID 30018256, 2018). "BMI1 is over-expressed in aggressive basal-like breast cancers where it promotes EMT and self-renewal and is thought to confer drug resistance." (PMID 30176939, 2018). "BMI1 is highly overexpressed in breast cancers and the downregulation of BMI1 in BCSC suppresses tumor growth and proliferation." (PMID 30018256, 2018). "For example, by decreasing TrkB and Bmi1 expression, miR-200c sensitizes breast cancer cells to doxorubicin treatment." (PMID 30537965, 2018). "Due to its oncogenic role as well as its function in the control of DNA damage response and repair, BMI1 stands as a very attractive target for breast cancer therapeutics." (PMID 28655885, 2017). "In some cases, inhibition of INK4A and ARF-mediated tumor suppression is critical for tumorigenesis and upregulation of BMI1 occurs in numerous cancer types including non-small cell lung cancer, colon cancer, breast cancer, and nasopharyngeal carcinoma." (PMID 29163782, 2017). "The purpose of this study was to determine the effects of downregulation of Bmi1 in breast cancer stem cells in order to target and eliminate the stem cell population in the tumor mass." (PMID 28418883, 2017). "In breast cancer cells, BMI1 can repress the dickkopf WNT signaling pathway inhibitor 1 and induce c-Myc expression to further activate BMI1 expression." (PMID 28914785, 2017). "Results regarding the inhibitory effect of hinokitiol in BMI1 expression through the induction of miR-494-3p suggest that hinokitiol has the potential to develop into a sensitization agent in breast cancer radiotherapy." (PMID 29100291, 2017). "Since many breast cancer cells express relatively high levels of BMI1, it is possible that this positive feed-back loop participates in maintaining that enhanced expression state and the cancer cell phenotype." (PMID 28587163, 2017). "There is a statistically significant correlation between Bmi1 expression levels and poor prognosis and survival as well as aggressiveness in human breast cancer patients." (PMID 28418883, 2017). "On the other hand, expression of Nanog, Bmi1, and Klf4 was inversely correlated with aggressive features of the breast cancer." (PMID 28422735, 2017). "The B-lymphoma Moloney murine leukemia virus insertion region-1 protein (BMI1) acts as an oncogene in various cancers, including breast cancer." (PMID 28655885, 2017). "On the other hand, expression of Nanog, Bmi1, and Klf4 was inversely correlated with aggressive features of the breast cancers." (PMID 28422735, 2017). "Silencing of BMI1 expression renders breast cancer cells more sensitive to doxorubicin and induces apoptosis." (PMID 28655885, 2017). "Our results suggest that miR-15a and miR-16 mediate the down-regulation of BMI1, which impedes DNA repair while elevated levels can sensitize breast cancer cells to doxorubicin leading to apoptotic cell death." (PMID 28655885, 2017). "BMI-1 was shown to be essential in the regulation of SNAIL expression in breast cancer and TWIST1 expression in head and neck cancer." (PMID 28968963, 2017). "Many studies have focused on Bmi1 expression and function in primary breast cancer cells from patients, or human breast cancer cell lines, and determined that loss of Bmi1 leads to loss of characteristics associated with CSCs." (PMID 28418883, 2017). "We plan to follow tumor growth for a longer time to better elucidate the effect of Bmi1 on growth and progression of the mammary tumors." (PMID 28418883, 2017). "It has been reported in breast cancer that patients with high levels of Bmi-1 had a more favorable outcome than patients with low expression of Bmi-1." (PMID 26894855, 2016).
breast carcinoma (continued). "Curcumin, a major phytochemical in turmeric (Curcuma longa), inhibits the proliferation and survival of many types of cancer cells, both in vitro and in vivo, and has been reported to reduce BMI1 expression in breast cancer cells." (PMID 27550987, 2016). "BMI-1 induced EMT and enhanced the invasion and metastasis of human nasopharyngeal epithelial cells and breast cancer cells, whereas BMI-1 silencing reduced cell motility and reversed EMT." (PMID 27145278, 2016). "We also show that PTC-209, a small molecule inhibitor of BMI1 gene expression induces cellular senescence and transcriptionally upregulates expression of miR-200c/141 cluster in breast cancer cells." (PMID 27105531, 2016). "We previously found that Bmi-1 can influence breast cancer cells proliferation and tumorigenicity through regulating pAKT." (PMID 27644439, 2016). "Many previous studies confirmed the strong relation between BMI-1 overexpression and different types of human tumors—breast cancer is one the most powerful examples of this relationship." (PMID 27506934, 2016). "In line with our results, silencing of BMI-1 in breast cancer cells was shown to impair Wnt signalling via downregulation of Wnt ligands (e.g. Wnt3a) and upregulation of Wnt inhibitors including DKK1." (PMID 26935956, 2016). "Further analysis of EMT markers revealed that the increased expressions of Bmi-1 in breast cancer cell lines were correlated to increased expression of vimentin and decreased expression of E-cadherin." (PMID 25734775, 2015). "Post-EMT breast cancer cells express cancer stem cell markers, including Bmi1, but show decreased ERα expression." (PMID 26023734, 2015). "Increasing evidence indicates that Bmi-1 is overexpressed in several cancer types, including leukemia, hepatocellular carcinoma, laryngeal carcinoma, lung cancer, breast cancer, and colon cancer." (PMID 26317630, 2015). "We demonstrated an inverse linear correlation of ERα or E-cadherin expression, with Bmi1 expression, when the percentage of positively stained cells for each protein was determined in human breast cancer tissues (P < 0.05)." (PMID 26023734, 2015). "In studying the role of Bmi1 in hormone-dependent and -independent breast cancer cells, we found that Bmi1 mRNA and protein levels were lower in ERα-positive than in ERα-negative cells." (PMID 26023734, 2015). "In summary, our results demonstrate that ERα can suppress EMT in human breast cancer cells through the transcriptional down-regulation of Bmi1 and its down-stream genes." (PMID 26023734, 2015). "In breast cancer, Bmi1 and E-cadherin levels were inversely related, while Bmi1 expression inversely correlated with the prognosis." (PMID 26023734, 2015). "In contrast to our findings, however, Wang's study found that Bmi1 expression was upregulated by the overexpression of ERα in another ERα-positive breast cancer cell line, MCF-7, while depletion of this protein caused a down-regulation of Bmi1." (PMID 26023734, 2015). "In order to quantify Bmi1 expression in breast cancer cells, we detected Bmi1 protein expression by Western blot in various breast cancer cell lines." (PMID 26023734, 2015). "In our study, we found that increased levels of Bmi-1 were correlated to EMT of breast cancer cells." (PMID 25734775, 2015). "Our data indicated while Bmi-1 protein was detected in all the tested breast cancer cell lines, its expression level was higher in MDA-MB-231 and Hs578t cells than the others." (PMID 25734775, 2015). "As was previously reported, post-EMT breast cancer cells express cancer stem cell markers, including Bmi1, but display decreased ERα expression." (PMID 26023734, 2015). "The reduction in the early phase (1 day) and induction in the late phase (2–7 days) of EMT process and migration of breast cancer cells post-IR are not only correlated to the expression levels of Bmi-1 post-IR, but also dependent on the expression of Bmi-1." (PMID 25734775, 2015).
breast carcinoma (continued). "Silencing Bmi-1 completely abolished the ability of the IR to alter, reduce or increase, the migration of breast cancer cells." (PMID 25734775, 2015). "In the present study, ERα upregulated the expression of the epithelial marker, E-cadherin, in breast cancer cells through the transcriptional down-regulation of Bmi1." (PMID 26023734, 2015). "Bmi-1 is important for the self-renewal of both normal and cancer stem cells, which is overexpressed in various tumors, such as breast cancer, lung cancer, colorectal cancer, prostate cancer and hepatocellular cancer." (PMID 25734775, 2015). "Since Bmi-1 was confirmed to promote cell proliferation and inhibit cell apoptosis and was involved in the increase of Akt phosphorylation in the human breast carcinoma cell line MCF-7." (PMID 26452029, 2015). "This conclusion is further supported by our dual luciferase reporter gene assay revealing increased/decreased activity of a BMI1 promoter-driven reporter gene in ERα silenced/overexpressing breast cancer cells." (PMID 26023734, 2015). "Positive staining for Bmi1 was analyzed for comparison with other routine markers of breast cancer including ERα, PR, HER2, and Ki-67." (PMID 24559156, 2014). "Taken together, these findings show the ERα-coupled Bmi1 regulation pathway plays an important role in regulation of the genes and biological behavior of breast cancer." (PMID 24559156, 2014). "Our results thus confirmed that knockdown of Bmi1 rendered the cells sensitive to chemotherapeutic drugs and revealed that Bmi1 is necessary for tumorigenicity of breast cancer cells." (PMID 25348805, 2014). "To corroborate the specificity of our observations, we undertook shRNA-mediated knockdown of Bmi1 in breast cancer cell lines with higher Bmi1 expression and investigated the effects on stemness properties." (PMID 25348805, 2014). "In the current study, we have explored the role of Bmi1 in regulating the stemness and drug resistance of breast cancer cells." (PMID 25348805, 2014). "This study also demonstrates a positive relationship between ERα-Bmi1 and cyclin D1 in ERα-positive breast cancer." (PMID 24559156, 2014). "Bmi-1 has been shown to play an important role in the regulation of stem cell self-renewal in breast cancer, where the activity of Bmi-1 is increased by Hh pathway activation." (PMID 26932376, 2014). "Consistent with this, we show here that Bmi1 overexpression induced EMT, a process closely associated with breast cancer metastasis, while its down-modulation reversed EMT." (PMID 25348805, 2014). "Combining the data with our results, we believe that there should be a close functional relationship between ERα and Bmi1, which also be crucial in regulation of breast cancers, especially in luminal-type carcinomas." (PMID 24559156, 2014). "At the same time, investigation has shown that Bmi1 expression is positively correlated with ERα status in breast cancer." (PMID 24559156, 2014). "Moreover, in breast cancer tissues activation of the ERα-coupled Bmi1 pathway generally correlated with high levels of cyclin D1, while loss of its activity resulted in aberrant expression of p16INK4a and a high Ki-67 index, which implied a more aggressive phenotype of breast cancer." (PMID 24559156, 2014). "While Bmi1 overexpression increased self-renewal and promoted EMT, its knockdown reversed EMT, reduced stemness, and rendered cells drug sensitive, thus highlighting a crucial role for Bmi1 in regulating the stemness and drug response of breast cancer cells." (PMID 25348805, 2014). "Bmi1 has been identified as an important regulator in breast cancer, but its relationship with other signaling molecules such as ERα and HER2 is undetermined." (PMID 24559156, 2014). "Subsequent studies by the same group have indicated that knock-down of Bmi-1 in breast cancer cell lines decreased their aggressive nature in vivo in tumor transplant studies." (PMID 25051360, 2014).
breast carcinoma (continued). "Few studies also found a correlation between Bmi1 expression and lymph node metastasis in breast cancer suggesting a role for Bmi1 in cancer metastasis." (PMID 25348805, 2014). "Taken together, our data suggested that Bmi1 regulates the stemness properties of breast cancer cells, at least in part, via regulating the expression of Nanog through the NFκB pathway." (PMID 25348805, 2014). "This investigation revealed a regulatory relation between Bmi1 and ERα, and demonstrated an ERα-coupled Bmi1 signaling pathway in breast cancer." (PMID 24559156, 2014). "The Bmi-1 proto-oncogene has been upregulated in a large number of cancers such as breast cancer, skin cancer, lymphoma, leukemia, and other cancers and is known to be a useful prognostic marker in many cancers." (PMID 23984324, 2013). "In breast cancer cells, Bmi1 activates the WNT pathway by repressing the expression of DKK family members, leading to increased c-Myc, which upregulates Bmi1 via a c-Myc binding site." (PMID 24312366, 2013). "Previous studies showed that Wnt signaling is implicated in self-renewal activity of colon cancer cells, while Bmi1 is regulated by Wnt signaling in breast cancer cells." (PMID 24312366, 2013). "As a member of the PcG family, Bmi-1 is overexpressed in various tumor types, including acute myeloid leukemia, lung cancer, ovarian cancer, nasopharyngeal carcinoma, breast cancer and colon cancer, suggesting that Bmi-1 represents a potential oncogene." (PMID 22967049, 2012). "In this report, we present the first evidence that Bmi-1 was correlated with radiation response in MCF-7 breast cancer cells." (PMID 22209830, 2012). "Over the past years, several studies have confirmed that Bmi-1 is over-expressed in all tumor cells and tissues of lung cancer, colorectal cancer, breast cancer, nasopharyngeal cancer, oral carcinoma, cutaneous carcinoma, and gastric cancer." (PMID 23691455, 2012). "In conclusion, we report the enhanced radiosensitivity of a breast cancer cell line after Bmi-1 inhibition using shRNA." (PMID 22209830, 2012). "Our results suggest that Bmi-1 inhibition play an additive effect to radiation therapy in MCF-7 mammary carcinoma cells providing a novel target for radio-sensitizing breast cancer." (PMID 22209830, 2012). "Studies over the past few years have proven that Bmi-1 directly participates in the oncogenesis, progression, invasion, and metastasis of breast cancer, head and neck tumor, as well as gastric cancer." (PMID 23691455, 2012). "Our previous study demonstrated that Bmi-1 promotes the invasion and metastasis of human breast cancer and predicts poor survival, the inhibition of Bmi-1 reverses the expression of EMT markers and inhibits the Akt/GSK3β/Snail pathway." (PMID 22209830, 2012). "Overexpression of miR-200c decreased Bmi-1 expression in breast cancer stem cells (BCSCs) and inhibited the formation of mammary ducts as well as tumors by normal mammary stem cells and BCSCs." (PMID 20936121, 2011). "This study demonstrates that Bmi-1 promotes the invasion and metastasis of human breast cancer and predicts poor survival." (PMID 21276221, 2011). "It is also important to note that Bmi-1 predicted poor prognosis in breast cancer, in accordance with other reports." (PMID 21276221, 2011). "Because we were interested in the expression status of Bmi-1 in normal and breast cancer cells, western blotting was performed to measure Bmi-1 protein levels." (PMID 21276221, 2011). "In summary, breast cancer shows a high prevalence of Bmi-1 expression, which is significantly correlated with aggressive features and unfavorable prognosis." (PMID 21276221, 2011). "Having demonstrated the significance of Bmi-1 in the overall survival prognosis of breast cancer patients, it will be our next focus to investigate the prognostic value of Bmi-1 in terms of disease-free survival and cancer-specific survival." (PMID 21276221, 2011).
breast carcinoma (continued). "The expression of EMT markers was analyzed to address the mechanism of Bmi-1-facilitated breast cancer metastasis." (PMID 21276221, 2011). "Bmi-1 can not only lead human mammary epithelial cells (HMECs) to bypass senescence and immortalize, but it also can play a key role in human breast cancer." (PMID 21276221, 2011). "The present study focuses on the expression patterns and roles of Bmi-1 in breast cancer tissues and cells to investigate the involvement of Bmi-1 in breast cancer metastasis." (PMID 21276221, 2011). "Taken together, these results provide evidence that breast cancers expressing Bmi-1 exhibit aggressive and metastatic properties." (PMID 21276221, 2011). "Our analysis of 252 primary breast cancer cases revealed that Bmi-1 expression was strongly correlated with larger tumor size (P < ***0.001), lymph node involvement (P < ***0.001), distant metastasis (P < ***0.001) and advanced clinical stage (P < ***0.001)." (PMID 21276221, 2011). "MiR-200c, which targets BMI1, is one of the important miRNAs that are epigenetically repressed in breast cancer cells." (PMID 21572997, 2011). "In this study, we identified and functionally characterized Bmi-1 as an important player in breast cancer progression." (PMID 21276221, 2011). "Similar to human fibroblasts, expression of Mel-18 negatively correlates with BMI1 in a number of breast cancer cell lines and breast tumors." (PMID 20170541, 2010). "Consistent with its role in stem cell self-renewal, BMI1 expression is thought to promote stem-ness in tumor cells, and BMI1 is considered an important marker of breast cancer stem cells." (PMID 20569464, 2010). "Our previous data also showed an inverse correlation between Bmi-1 and Mel-18 expression at protein level in breast cancer and gastric cancer." (PMID 21059209, 2010). "We also reported that Mel-18 overexpression in breast cancer cell line MCF7 results in downregulation of BMI1 and reduction of transformed phenotype." (PMID 20170541, 2010). "Overexpression of key PcG proteins such as BMI1 has been found in several human malignancies including breast cancer, colorectal cancer, nasopharyngeal carcinoma, melanoma, gastric cancer, and bladder cancer." (PMID 20170541, 2010). "We have previously reported that p16 and AKT are potential cancer-relevant targets of BMI1 and Mel-18 in human fibroblasts and breast cancer cells respectively." (PMID 20170541, 2010). "In summary; we have in the present study demonstrated for first time that the levels of Mel-18 and Bmi-1 is different in normal tissue from breast cancer patients compared to breast tissue from non cancer controls." (PMID 21162745, 2010). "Previous studies found that INK4A/ARF locus and AKT/PKB pathway are two important cancer relevant target of Bmi-1 in gastric and breast cancers." (PMID 20723236, 2010). "Overexpression of Bmi-1 has been found in several human malignancies including breast cancer, colorectal cancer, nasopharyngeal carcinoma, melanoma, gastric cancer, and bladder cancer." (PMID 21059209, 2010). "Our previous data showed an inverse correlation between Bmi-1 and Mel-18 expression in breast cancer cells and breast cancer tissues." (PMID 21059209, 2010). "The opposite role of BMI1 and Mel-18 in human fibroblasts and breast cancer cells is an interesting finding." (PMID 20170541, 2010). "In normal tissue from breast cancer patients Bmi-1 mRNA was up-regulated, compared to tissue from breast without history of malignant disease." (PMID 21162745, 2010). "Our previous studies suggest that Mel-18 is a physiologic regulator of Bmi-1 expression and transcriptionally down-regulates Bmi-1 expression during senescence in human fibroblasts and acts as a tumor suppressor in breast cancer." (PMID 21059209, 2010).